CCR2 (C-C motif chemokine receptor 2)
Diseases named in the same sentence as CCR2 in open-access papers (continued):
Sharing a sentence is not in itself a finding about the gene and the disease.
breast cancer (continued). "Therefore, this study highlights the potential therapeutic value of targeting the CXCR2 or CCR2 pathway as a novel strategy to combat paclitaxel-resistant breast cancer." (PMID 37821959, 2023). "Recently, it was shown that the deletion of CCR2 in breast cancer cells leads to a reduction of tumor growth through changes in the TME, including increased infiltration and activation of CD8+ T cells and cross-presenting CD103+ DCs, and the upregulation of MHCI expression." (PMID 37478172, 2023). "Breast cancer cases may benefit from therapies that blockade the EZH2-CCL2/CCR2 cell revulsive axis or its amplifier IL-10-EGFR pathway for the alleviation of cancer growth and dissemination." (PMID 36038549, 2022). "Previously, we demonstrated that CCR2-KO in breast cancer cells inhibited tumor growth." (PMID 35405500, 2022). "Polish scientists determined plasma CCR2 levels in 100 patients with breast cancer (BC) and controls that involved 35 patients with benign breast tumors and 35 healthy women, as many cancer cells may express chemokines and chemokine receptors." (PMID 35888126, 2022). "•CCL2/CCR2 signaling in breast cancer cells depend on interactions with MET." (PMID 35405500, 2022). "Thus, inhibition of TAMs recruitment by targeting CCL2 or CCR2 has successfully reduced tumor burden in melanoma, breast cancer, and so on." (PMID 35844580, 2022). "Furthermore, SMAD3 cooperation with p42/44MAPK was found to be important in CCL2/CCR2 mediated breast cancer cell survival and motility." (PMID 33888841, 2021). "Previous studies showed that CCL2 significantly stimulated CCR2 signaling in breast cancer cells." (PMID 33888841, 2021). "The utilization of cationic polymeric NPs carrying CCR2 siRNA could block the expression level of CCR2 in monocytes, suppress monocyte recruitment in tumor tissues, and enhance anti-tumor effects in the breast cancer model." (PMID 34576180, 2021). "The CC chemokine ligand (CCL2)-CCR2 axis is involved in multi-tyrosine kinase inhibition and microtubule inhibition resistance in the colon and prostate cancer cells, and CCR2 promotes cell growth and cell cycle progression via Src and Akt activation in breast cancer cells." (PMID 33406639, 2021). "Many other preclinical studies on hepatocellular carcinoma, prostate cancer, and breast cancer showed that either depletion of CCR2 or breaking the CCL2-CCR2 interaction has an impact on inhibition of TAMs recruitment and tumor regression or inhibition of metastasis." (PMID 33919517, 2021). "This hypothesis needs to be further fully investigated and targeting LDHA combined with CCL2/CCR2 antagonists may provide a better therapeutic outcome for breast cancer." (PMID 34178639, 2021). "It was reported that ablation of CCR2 could inhibit breast cancer bone metastasis by suppressing macrophages." (PMID 33318300, 2020). "Indeed, the blockade of the CCL2-C-C Motif Chemokine Receptor 2 (CCR2) axis, involved in breast cancer cell metastatic seeding in the lungs and recruitment of metastasis-associated macrophages, has provided therapeutic benefit in fibrosarcoma models." (PMID 33193295, 2020). "If these data can be confirmed beyond breast cancer models in mice, the utility of targeting CCR2 may well extend beyond its effects on immunosuppressive cells in the tumor microenvironment to encompass direct effects on tumor cells themselves." (PMID 33322474, 2020). "The results showed that the levels of CCL2 and CCR2 were significantly higher in breast cancer patients, which could be used as a molecular marker for breast cancer diagnosis." (PMID 32253815, 2020). "In addition, Ly6C+CCR2+ monocytes that trigger metastasis of mammary tumors were also found to be higher, which is inconsistent with the expression of CCL2, which is known to enhance the establishment of Ly6C+CCR2+ monocyte-assisted lung metastasis." (PMID 33628730, 2020).
breast cancer (continued). "In summary, it is possible that ALDH1A1 expression and activity in DCIS.com and SUM225 CCR2-overexpressing breast cancer cells may facilitate cell growth through metabolites that activate oncogenic pathways." (PMID 31208996, 2019). "miR-150-5p was negatively related CCR2 mRNA in in breast cancer tissues." (PMID 30733855, 2019). "In addition to p42/44MAPK, CCL2/CCR2 activates multiple signaling pathways in breast cancer cells including: PKC, Rho and SRC to regulate growth and motility." (PMID 31208996, 2019). "CCR2 mRNA was higher in breast cancer tissues than the adjacent normal tissues." (PMID 30733855, 2019). "CCR2 overexpression in SUM225 breast cancer cells enhanced formation of breast carcinomas." (PMID 31208996, 2019). "Besides, antagonism therapy against CCR2 strikingly suppressed estrogen-triggered breast cancer growth, vascularization, macrophage infiltration and metastasis in xenograft tumor models, suggesting a critical role of CCL2-CCR2 axis in HR+ tumor progression." (PMID 29934505, 2018). "However, treatment of PyMT mice with the chemotherapeutic agent, doxorubicin, increases protein levels of CCR2 ligands CCL2 and CCL12 in the tumor stromal area, and promotes the recruitment of CCR2+ monocytes into the mammary tumors." (PMID 30483271, 2018). "However, the concentration of CCR2 in patients with breast cancer was significantly lower than entire control group (p<0.001)." (PMID 30151375, 2018). "To date, there are no reports of the diagnostic usefulness of CCL2 and CCR2 serum or plasma levels in breast cancer patients." (PMID 30151375, 2018). "For example, CCL2 produced by breast cancer cells and stromal cells recruits CC chemokine receptor 2 (CCR2)-positive inflammatory monocytes to the lungs; then these inflammatory monocytes secrete vascular endothelial growth factor to promote breast cancer cell extravasation and lung metastasis." (PMID 28356139, 2017). "The CCR2-64I polymorphism, which slightly impairs capacity to transduce CCL2 signals, is underrepresented in patients with breast cancer, and this might provide protection from tumour formation through reduced recruitment of tumour-promoting macrophages." (PMID 28077158, 2017). "Additionally, according to fluorescent IHC staining of the 1° IRISOE mammary tumors only F4/80+ (mouse macrophage-specific biomarker) cells are CCR2+." (PMID 29262555, 2017). "Taken together, our data support the validity of CCR2 as a therapeutic target in breast cancer." (PMID 27820834, 2016). "We examined the behavior of these mammary carcinomas in mice carrying targeted deletions of Ccl2 or Ccr2, as well as wild type mice treated with a small molecule antagonist of CCR2, and explored the effects of this chemokine ligand/receptor pair on the tumor microenvironment." (PMID 27820834, 2016). "The MMTV-neu model may specifically highlight this discrepancy since the phenotypes of Ccl2-/- and Ccr2-/- mice are similar in polyoma middle T antigen-driven mammary carcinoma." (PMID 27820834, 2016). "In the primary tumors developed by 4T1 mouse breast cancer cells, inhibition of either CCR2 or CXCR2 can reduce the number of macrophages, which also suggests the involvement of multiple chemokine signals in the macrophage accumulation in the tumor microenvironment." (PMID 26275794, 2015). "Furthermore, CCL2/CCR2 (CCL2 receptor) chemokine signaling seems to be implicated in cell migration and its overexpression is associated with breast cancer metastasis to both lung and bone." (PMID 24591761, 2014). "For example, a recent study reported that CCR2 blockade could enhance the efficacy of anti-PD-1 therapy in in vivo lung and mammary tumour models by reducing macrophage frequency in tumours; thereby reducing Treg expansion and increasing effector T cell infiltration." (PMID 40385641, 2025). "Therefore, inhibition of CCL2 or CCL2/CCR2 may be a potential approach to the treatment of breast cancer." (PMID 36403055, 2022).
breast cancer (continued). "Moreover, PTX-elicited extracellular vesicles contain high amount of annexin A6 (ANXA6), a Ca2+-binding protein, which can promote increased CCL2 expression in endothelial cells and consequent recruitment of inflammatory monocytes expressing CCR2, thereby promoting lung metastasis in breast cancer." (PMID 35280672, 2022). "Moreover, ALDH1A1 contributed to CCR2-mediated breast cancer cell growth and invasion." (PMID 35173149, 2022). "In addition, just prior to submission of our paper, CCR2 expression by murine breast cancer cells was shown to support immune evasion by inhibiting dendritic cell infiltration and maturation, suppressing cytotoxic T cell activity, decreasing MHC class I expression and upregulating PD-L1 expression." (PMID 33322474, 2020). "By understanding the molecular and cellular mechanisms of CCL2/CCR2 signaling facilitating growth and invasion of cancer cells, we may better understand the potential effects of CCL2 or CCR2 inhibitors on tumor progression, and design improved strategies for treatment of invasive breast cancer." (PMID 31208996, 2019). "Interestingly, a recent study using a mouse model of breast cancer showed that TAMs are recruited via CCR2 signaling to primary tumors where they induce CXCR4 expression in response to tumor-derived TGFβ and then migrate toward the blood vessel via CXCL12 to promote intravasation of cancer cells." (PMID 30483271, 2018). "Here, we found the following: first, CCL2/CCR2 interaction promoted A549 cell proliferation, migration and invasion, although to a lesser extent compared with those in other cancer cells, such as prostate and breast cancer cells, which was indicative of tissue-specific functions for CCL2 signaling." (PMID 28424406, 2017). "Our data indicate the importance of evaluating CCR-2 expression in TEpCs as well as CCL-2 expression in TEpC and spindle-shaped stromal cells, because the pathways that produce CCR-2 and its ligands may provide targets for the prevention of breast cancer progression and metastasis." (PMID 28420351, 2017). "Previous studies have demonstrated that CCR2 high expression in many malignant tumor tissues was positively correlated with disease progression and worse outcomes, including prostate cancer, lung cancer, liver cancer, breast cancer, colorectal cancer and pancreatic cancer." (PMID 26992207, 2016). "Besides, an antagonist of CCR2 could abolish alcohol-stimulated migration or growth in colorectal and breast cancer." (PMID 26992207, 2016). "This is consequential, because recruitment of CCR2 positive inflammatory Mø has been shown to occur preferentially in the lung pre-metastatic niche rather than in the primary mammary tumors of late-stage PyMT-induced breast cancers, which instead recruit CCR2-negative, CSF-1 dependent TAMs." (PMID 23372702, 2013). "We conducted an examination of the CCR2/PPARα/ATGL pathway in adipose tissues adjacent to normal breast tissue (non‐peritumoral AT) and those adjacent to breast cancer tissue (peritumoral AT) from the same patients." (PMID 41160815, 2026). "Taken together, our findings indicate that in breast cancer patients, obesity enhances the activation of the FA/HIF‐1α/CCL2 axis in tumor tissues and the CCL2/CCR2/PPARα axis in adjacent adipose tissue." (PMID 41160815, 2026). "Overall, these data indicate that CCR2 overexpression increases responsiveness to CCL2 and HGF in SUM225 breast cancer cells." (PMID 40736024, 2025). "In previous studies, CCR2 and MET co-expression correlated with the invasiveness of breast cancer cells." (PMID 40736024, 2025). "In pancreatic, colon and breast cancers, CCL2 and CCR2 overexpression correlates with unfavorable prognosis." (PMID 38973385, 2024). "More interestingly, aerobic exercise plays a protective role in primary cancer development and progression by regulating the levels of chemokines CCL2, CCL5, and their related receptors CCR2, and CCR5 in breast cancer." (PMID 36976529, 2023).
breast cancer (continued). "Signalling between CCR2 and its ligand CCL2 is related to the disease progression of various cancers, such as breast cancer and melanoma." (PMID 35999359, 2023). "Here, we sought to understand the molecular mechanisms through which CCL2/CCR2 signaling regulated DCIS progression using in vitro and in vivo breast cancer models." (PMID 35405500, 2022). "Previous studies have reported that overexpression of CCL2 and its receptors, CCR2, and CCR4, in human cancers, promote lung cancer, breast cancer, and HNSCC development via regulation of angiogenesis, cell proliferation, and migration." (PMID 35177591, 2022). "Breast cancer can be treated with CCL2 neutralizing antibodies and the same outcomes were observed by targeting CCR2." (PMID 36403055, 2022). "Through analysis of data obtained from reverse phase protein profiling in a previous study, we found that CCL2 treatment of MCF10CA1d breast cancer cells enhanced phosphorylation of MET receptors, which was reduced in CCR2 knockout cells." (PMID 35405500, 2022). "Overall, these data indicate that: CCL2 triggers interactions among CCR2, MET and SRC in breast cancer cells, and CCL2 regulates MET phosphorylation through CCR2- and SRC-dependent mechanisms." (PMID 35405500, 2022). "In a breast cancer model, CCL2 recruited CCR2-expressing inflammatory monocytes to the lung to facilitate pulmonary metastasis, while we have shown a similar role for CCL2 in liver metastasis of colorectal cancer." (PMID 36241867, 2022). "Activation of several Gi/o-coupled chemokine receptors, including CCR2, CXCR1, and CXCR2, by their cognate ligands was found to stimulate CSC activity in HER2+ breast cancer." (PMID 35406489, 2022). "Future studies would involve in-depth isotope tracing studies on breast cancer cell lines and tissues to determine the contributions of glucose and glutamine to CCL2/CCR2- and MET-mediated metabolism during DCIS progression." (PMID 35405500, 2022). "Even so, combination of CCR2 blockade with anti-PD1 therapy enhanced anti-tumor responses in many preclinical cancer models (melanoma, breast cancer)." (PMID 35211124, 2022). "In mice, Ly6C+/CCR2+ cells, defined as inflammatory monocytes, have been shown to contribute to TAM accumulation and maintenance in a mouse mammary tumor model and the establishment of pulmonary metastases derived from mouse or human breast cancer cells." (PMID 35664746, 2022). "ER+ breast cancer cells proliferate, migrate, and invade, in part due to up-regulated CCL2 interacting with its receptor, CCR2." (PMID 36403055, 2022). "The study of the non-coding function of CCR2 mRNA shows that its 3′UTR inhibits breast cancer cell metastasis by repressing epithelial–mesenchymal transition (EMT) in vitro and suppresses breast cancer metastasis in vivo." (PMID 35454884, 2022). "CCR2, with distinct expression modes in LUAD, was different from other cancer types such as breast cancer, pancreatic ductal adenocarcinoma, or prostate cancer." (PMID 33949150, 2021). "Tregs have been shown to highly infiltrate mammary tumors of MMTV-PyMT mice, depending in part on CCR2 expression on Tregs." (PMID 34632244, 2021). "Neoadjuvant chemotherapy was shown to induce release of microvesicles from breast cancer cells containing more CCL2 molecules; it also enhanced infiltration of Ly6C+CCR2+ monocytes recruitment in the lung pre-metastatic site." (PMID 34386431, 2021). "Through recruitment of CCR2-expressing monocytes, CCL2 has been shown to promote pulmonary metastasis in mouse models of breast cancer." (PMID 33968034, 2021). "Prolonged blood circulation, high tumoritropic accumulation, proactive recruitment capacity from CCL2/CCR2, and α4/VCAM‐1 active targeting property were achieved by QE‐loaded BS‐NPs@MφCM NPs, resulting in the inhibition of lung metastasis of breast cancer." (PMID 33898169, 2021).
breast cancer (continued). "Blockade of the CCL2/CCR2 axis led to reduction of monocyte infiltration in multiple TIME and inhibits breast cancer cell metastatic seeding." (PMID 31611871, 2019). "Using 3D Matrigel: Collagen cultures of SUM225 and DCIS.com breast cancer cells, this study characterized the mechanisms of CCL2/CCR2 signaling in cell growth and invasion." (PMID 31208996, 2019). "In breast cancer, CCL2/CCR2 axis coordinates cells survival and motility through Smad3 and MAPK-dependent mechanisms." (PMID 31501414, 2019). "To elucidate the mechanisms through which CCL2/CCR2 signaling regulated breast cancer cell growth and invasion, we first analyzed the effects of CCL2 treatment on DCIS.com and SUM225 breast cancer cell growth and invasion in 3D Matrigel: Collagen cultures." (PMID 31208996, 2019). "Using 3D Matrigel: Collagen cultures of SUM225 and DCIS.com breast cancer cells, this study characterized the mechanisms through which CCL2/CCR2 signaling regulated cell growth and invasion." (PMID 31208996, 2019). "Despite the differences in how these cells were generated, CCR2 shRNA knockdown and CRISPR knockout both led to a reduction in breast cancer survival and invasion in animal models." (PMID 31208996, 2019). "Out of all the known chemokines, breast cancer cells express the CCL2 chemokine, the receptor of which is CCR2." (PMID 30151375, 2018). "Activation of the CCL2/CCR2 axis increased secretion of CCL3 by MAMs, which in turn facilitated metastatic seeding of breast cancer cells in the lung." (PMID 29594035, 2018). "The CCR2 3′UTR acted as a ceRNA for STARD13 and helped to inhibit cell metastasis by repressing EMT in breast cancer." (PMID 30545369, 2018). "Therefore, CCR2 could also be a potential target for inhibiting cell invasiveness in breast cancer." (PMID 29594759, 2018). "Recently, there are several researches in Hela cells, breast cancer, colon carcinoma and melanoma showing CCL2/CCR2 axis is related to the activation of MAPK pathways in ERK1/2, p38, and JNK." (PMID 26701209, 2016). "Here, we used a mouse model of breast cancer in which the MMTV LTR drives activated HER2/neu (MMTV-neu) to investigate how CCL2 and CCR2 affect tumor development." (PMID 27820834, 2016). "Understanding the specific mechanisms that regulate CCL2 and HGF expression are regulated in breast cancer may enable us to predict when CCR2 and MET signaling may be altered during breast cancer progression." (PMID 40736024, 2025). "In summary, these findings on CCL2/CCR2 and HGF/MET signaling in early-stage breast cancer could be used to tailor treatments for patients with DCIS." (PMID 40736024, 2025). "CCL2/CCR2 and HGF/MET cooperate to enhance breast cancer progression and metabolic reprogramming." (PMID 40736024, 2025). "Furthermore, subsets of CD8 + T cells displayed expression of CCR2 and CCR4, albeit to a lower extent than CXCR3, in human CRC, pancreatic neuroendocrine and breast cancers." (PMID 40595293, 2025). "In addition, some populations of cells exclusively expressed CCR2 or MET27, suggesting variations in CCR2 and MET signaling within breast cancer cell lines." (PMID 40736024, 2025). "CCL2/CCR2 and HGF/MET signaling pathways are upregulated in breast cancers." (PMID 40736024, 2025). "CCR2 and MET signaling in breast cancer cells may induce expression of factors that regulate accumulation of fibroblasts, macrophages, and endothelial cells such as MMPs, TGF-β." (PMID 40736024, 2025). "Given the cooperative effects between CCL2 and HGF on breast cancer cells, we hypothesized that targeting CCR2 or MET alone would inhibit DCIS progression more effectively than inhibiting CCR2 or MET alone." (PMID 40736024, 2025). "Breast carcinomas, regardless of subtype, show increased CCR2 expression, compared to normal breast." (PMID 40736024, 2025). "CCR2 recruits Treg cells to the TME in melanoma and breast cancer." (PMID 39000453, 2024).